GPM6A (glycoprotein M6A)
Description:
Involved in neuronal differentiation, including differentiation and migration of neuronal stem cells. Plays a role in neuronal plasticity and is involved in neurite and filopodia outgrowth, filopodia motility and probably synapse formation. GPM6A-induced filopodia formation involves mitogen-activated protein kinase (MAPK) and Src signaling pathways. May be involved in neuronal NGF-dependent Ca(2+) influx. May be involved in regulation of endocytosis and intracellular trafficking of G protein-coupled receptors (GPCRs); enhances internalization and recycling of mu-type opioid receptor.
Synonyms: M6a; GPM6
Tractability: Antibody: UniProt places it where antibodies can reach, with medium confidence; UniProt predicts a signal peptide or a membrane-spanning region; its Gene Ontology location is reachable by antibodies, with medium confidence. PROTAC: ubiquitination databases record sites on it; its protein half-life has been measured.
Gene: Protein-coding gene on chromosome 4 (175,632,934 to 176,003,069, reverse strand). Ensembl gene ENSG00000150625.
Subcellular location: Cell membrane; Cell projection, axon; Cell projection, growth cone; Cell projection, dendritic spine; Cell projection, filopodium; Cell projection, neuron projection
Gene Ontology:
Molecular function: protein binding; calcium channel activity
Biological process: neuron migration; stem cell differentiation; neural retina development; neuron projection development; neuron projection morphogenesis; positive regulation of filopodium assembly; regulation of filopodium assembly; synapse assembly; calcium ion transmembrane transport; regulation of synapse organization
Cellular component: extracellular exosome; extracellular vesicle; axonal growth cone; filopodium; neuron projection; neuronal cell body; plasma membrane; axon; dendritic spine; glutamatergic synapse; growth cone; membrane; parallel fiber to Purkinje cell synapse; presynapse; presynaptic active zone membrane
Genetic constraint (gnomAD): Loss-of-function variants: 1 observed, 13.12 expected, observed/expected ratio (o/e) 0.0762, 90% interval 0.026 to 0.36. The upper end of that interval is the gene's LOEUF score, 0.36, which puts it in group 1 of 6, group 1 being the genes least tolerant of losing a copy. Missense variants: 150 observed, 244.3 expected, observed/expected ratio (o/e) 0.61, 90% interval 0.54 to 0.7. Synonymous variants: 86 observed, 86.9 expected, observed/expected ratio (o/e) 0.99, 90% interval 0.83 to 1.18.
Homologues: Orthologues: chimpanzee GPM6A (100% identical), macaque GPM6A (100% identical), guinea pig GPM6A (99% identical), mouse Gpm6a (99% identical), rabbit GPM6A (96% identical), rat Gpm6a (96% identical), tropical clawed frog gpm6a (96% identical), pig GPM6A (88% identical), zebrafish gpm6ab (82% identical), Drosophila melanogaster M6 (27% identical), Caenorhabditis elegans nmgp-1 (19% identical). Paralogues in human: GPM6B (56% identical), PLP1 (36% identical).
Diseases named in the same sentence as GPM6A in open-access papers:
GPM6A is named in the same sentence as 42 diseases in open-access papers, as found by Europe PMC text mining. Sharing a sentence is not in itself a finding about the gene and the disease. The quoted sentences say what the papers report.
schizophrenia (12 papers, 2017 to 2026). A major psychotic disorder characterized by abnormalities in the perception or expression of reality. "Several SNPs in GPM6A have been associated with various neuropsychiatric diseases, such as schizophrenia and depression." (PMID 41350806, 2025). "GPM6A is associated with psychiatric traits, such as bipolar diseases, schizophrenia, depression, Alzheimer's disease, and claustrophobia (e.g.,51–55)." (PMID 36581688, 2022). "SNVs in the GPM6A gene or alterations in GPM6A expression are linked to neurological disorders such as schizophrenia, depression, and Alzheimer’s disease." (PMID 35328011, 2022). "In humans, alterations in M6a levels or polymorphisms in GPM6A, are associated with depression, schizophrenia, claustrophobia, bipolar disorders, and learning disabilities." (PMID 32848694, 2020). "Genetic variations or alterations in GPM6A expression are linked to neurological disorders such as schizophrenia, depression, and Alzheimer’s disease." (PMID 32848694, 2020). "Downregulation of GPM6A mRNA levels has been shown in the hippocampus of depressed suicide victims and the association of GPM6A gene with schizophrenia, bipolar disorders, and claustrophobia has been described." (PMID 30233315, 2018). "Similarly, GPM6a has been linked to autism and schizophrenia and is suggested to act as a nerve growth factor-gated calcium channel." (PMID 41386992, 2026). "Therefore, further investigations on COMT, RASSF1 and GPM6A on larger population are warranted to validate our findings and further elucidate the association between schizophrenia and variations in these genes." (PMID 35528814, 2022). "As previously report, the rs13142920 polymorphism is located in an intronic area of GPM6A that has an associated to schizophrenia and is likely to be linked to causative variants that can directly affect the appearance of schizophrenia by acting as an enhancer in the transcription process." (PMID 35528814, 2022). "Our findings suggested that the GPM6A variant might contribute to schizophrenia risk." (PMID 35528814, 2022). "By integrating the results from different prediction approaches, they identified six top candidates that represent promising causal genes for schizophrenia (CNTN4, GATAD2A, GPM6A, MMP16, PSMA4, and TCF4), including the GPM6A gene." (PMID 35328011, 2022). "Among the 41 prioritized causal genes, CNTN4, GATAD2A, GPM6A, MMP16, PSMA4, and TCF4 represent the most promising causal genes for schizophrenia." (PMID 29540662, 2018). "Of note, five (CNTN4, GATAD2A, GPM6A, MMP16, and TCF4) of the top six causal genes are involved in neurodevelopment, further supporting the neurodevelopmental hypothesis of schizophrenia." (PMID 29540662, 2018).
depression (6 papers, 2020 to 2025). "Gpm6a is involved in neuronal polarity and is downregulated in depression." (PMID 39774335, 2025). "Among these genes, GPM6A is already known to be involved in promoting the formation of synapses, with evidence of involvement in brain signaling pathways of psychiatric disorders such as depression." (PMID 37764111, 2023). "Moreover, the same study identified several candidate genes for depression phenotypes, such as GPM6A, HDAC7, VDR and QRICH1." (PMID 37764111, 2023).
Alzheimer disease (5 papers, 2018 to 2024). A progressive, neurodegenerative disease characterized by loss of function and death of nerve cells in several areas of the brain leading to loss of cognitive function such as memory and language. "Despite its secretion in EVs under stress conditions, and its association with Alzheimer’s disease, there is currently no documented report specifically linking GPM6A to human lungs or pulmonary EVs." (PMID 38891077, 2024). "Additionally, GPM6A is possibly involved in Alzheimer’s disease." (PMID 38891077, 2024).
lung carcinoma (5 papers, 2018 to 2025). "Apart from that, the MIR99AHG/miR‐218‐5p/GPM6A axis has a twofold lung cancer inhibitory effect in lung adenocarcinoma through the non‐coding tumor suppressor gene MIR99AHG." (PMID 39957375, 2025). "GPM6A expression level in lung carcinoma patients is lower than that in normal samples, suggesting that it is a gene closely related to lung carcinoma." (PMID 39957375, 2025). "This article reviewed the mechanisms of GPM6A in colorectal cancer, liver cancer, lung cancer, glioblastoma, and other malignant tumors, and made a “one‐stop” summary of the relevant mechanisms." (PMID 39957375, 2025). "MIR99AHG/miR‐218‐5p/GPM6A axis has twofold lung cancer inhibitory effect in lung adenocarcinoma." (PMID 39957375, 2025). "In contrast, GPM6A upregulation inhibited the progression of lung cancer." (PMID 36405247, 2022). "GPM6A expression was significantly lower in lung cancer samples than in normal specimens." (PMID 36405247, 2022). "Decreased GPM6A expression may lead to the decrease of filopodia and the increase of lamellipodia, resulting in rapid metastasis of cancer cells, affecting the prognosis of lung cancer patients." (PMID 39957375, 2025). "However, studies on the relevance of GPM6A in lung cancer are limited." (PMID 36405247, 2022). "Thus, GPM6A may be a potential target for the treatment of human lung cancer." (PMID 39957375, 2025). "Thus, GPM6A could be a possible treatment target for lung cancer therapy." (PMID 36405247, 2022). "Therefore, GPM6A could be a possible treatment target for lung cancer therapy." (PMID 36405247, 2022). "Next, three tumor suppressive ceRNA modules (ANXA2P1/miR-20b-5p/FAM241A, MIR99AHG/miR-218-5p/GPM6A, and SH3RF3-AS1/miR-34a-5p/HECW2) were analyzed to assess significance of their lung cancer survival rate prediction values." (PMID 36289596, 2022). "In addition, the second tumor suppressor MIR99AHG/miR-218-5p/GPM6A axis provides two-fold lung cancer inhibition via non-coding tumor suppressor gene MIR99AHG in lung adenocarcinoma and miR-218-5p affects lung adenocarcinoma progression." (PMID 36289596, 2022).
hepatocellular carcinoma (4 papers, 2022 to 2025). A malignant tumor that arises from hepatocytes. "CircCCNB1 can act as a miR-106b-5p inhibited GPM6A expression to promote hepatocellular carcinoma progression." (PMID 38434987, 2024). "In GPM6A‐overexpressed hepatoma cells, the function of microRNA‐96 was inhibited significantly." (PMID 39957375, 2025). "The levels of GPM6A found in hepatocellular carcinoma (HCC) tissue are much lower than those in pericancerous liver tissue, and the oncogenic microRNA‐96 function is significantly suppressed in liver cancer cells with overexpression of GPM6A." (PMID 39957375, 2025).
colorectal cancer (3 papers, 2022 to 2025). A primary or metastatic malignant neoplasm that affects the colon or rectum. "Decreased GPM6A expression was found in highly differentiated colorectal cancer (CRC) tissues, while higher expression levels were observed in minimally differentiated or undifferentiated colon cancer tissues." (PMID 39957375, 2025). "In colorectal cancer, the up-regulation of GPM6A was closely related to a poorer overall survival." (PMID 35883571, 2022). "While GPM6A has been identified as a potential oncogene in lymphoid leukemia, and contributes to the poor prognosis of colorectal cancer, its role in GB has never been reported." (PMID 35883571, 2022).
glioblastoma (3 papers, 2022 to 2025). The most malignant astrocytic tumor (WHO grade IV). "The MIR99AHG/miR-218-5p/GPM6A axis may display a stemness signature via GPM6A that plays an important role during early events of cellular differentiation and is associated with invasiveness of glioblastoma stem cells." (PMID 36289596, 2022). "Protein tyrosine phosphatase receptor type Z1 (PTPRZ1) and GPM6A are essential for the formation of glioblastoma (GB) stem cells (GBSC) spheres." (PMID 39957375, 2025). "We then analyzed, in the glioblastoma database of the Cancer Genome Atlas (TCGA), the correlations between the expression GPM6A and other genes potentially involved in GB cells invasion." (PMID 35883571, 2022). "Our results suggest that blocking GPM6A or PTPRZ1 could represent an interesting approach in the treatment of glioblastoma since it would simultaneously target proliferation, invasion, and radioresistance." (PMID 35883571, 2022). "All of our results suggest that blocking GPM6A or PTPRZ1 could represent an interesting approach in the treatment of glioblastoma, since it would simultaneously target proliferation, invasion, and radioresistance." (PMID 35883571, 2022).
lung adenocarcinoma (3 papers, 2022 to 2025). A carcinoma that arises from the lung and is characterized by the presence of malignant glandular epithelial cells. "In addition to CRC, lung adenocarcinoma, liver cancer, and GB, there are other malignancies associated with GPM6A gene and its abnormal protein function." (PMID 39957375, 2025). "The expression of GPM6A in lung adenocarcinoma was lower than that in adjacent tissues or normal lung tissues, and similar result was observed in lung adenocarcinoma cells." (PMID 39957375, 2025). "GPM6A upregulation inhibits the development of lung adenocarcinoma cells, delays tumor growth, and reduces tumor weight." (PMID 39957375, 2025). "Functional studies have shown that upregulation of GPM6A inhibits the development of lung adenocarcinoma cells, whereas downregulation of GPM6A enhances their migration, proliferation, and EMT." (PMID 39957375, 2025). "Downregulation of GPM6A enhanced the EMT of lung adenocarcinoma cells and EMT is necessary for most malignant tumor metastasis." (PMID 39957375, 2025). "In the Oncomine dataset, GPM6A expression was significantly lower in lung adenocarcinoma tissues (42 samples) than in normal lung tissues (63 samples) (Hou lung)." (PMID 36405247, 2022). "In this study, we analysed GPM6A in 33 types of tumors in TCGA dataset and also the GPM6A expression between lung adenocarcinoma and adjacent tissues in the Oncomine database." (PMID 36405247, 2022). "GPM6A mRNA expression was lower in 15 types of cancers including lung adenocarcinoma in TCGA dataset." (PMID 36405247, 2022). "Real-time quantitative polymerase chain reaction (RT-qPCR) was performed to detect GPM6A expression in human lung adenocarcinoma cell lines (A549 and H1299) and normal pulmonary epithelial cells (BEAS-2B)." (PMID 36405247, 2022). "GPM6A expression was also lower in lung adenocarcinoma than in adjacent tissues in the Oncomine database." (PMID 36405247, 2022). "Further function study showed that GPM6A inhibits the propagation and migration of lung adenocarcinoma cells." (PMID 36405247, 2022). "The CCK8 assay showed that GPM6A downregulation promoted the growth of the two lung adenocarcinoma cell lines." (PMID 36405247, 2022). "In the current study, GPM6A mRNA expression was lower in 15 types of tumors including lung adenocarcinoma in TCGA dataset." (PMID 36405247, 2022). "GPM6A expression was lower in lung adenocarcinoma than in normal lung tissues or adjacent tissues in the Oncomine dataset." (PMID 36405247, 2022). "In conclusion, GPM6A suppresses lung adenocarcinoma progression via inhibition of the PI3K/AKT pathway." (PMID 36405247, 2022). "The transwell and wound healing assays showed that GPM6A upregulation suppressed the migration abilities of lung adenocarcinoma cells." (PMID 36405247, 2022). "In the current study, GPM6A expression at the mRNA level was lower in lung adenocarcinoma than in normal or adjacent lung tissues." (PMID 36405247, 2022). "In conclusion, GPM6A acts as a tumor suppressor and inhibits the proliferation and migration of lung adenocarcinoma via inhibition of the PI3K/AKT pathway." (PMID 36405247, 2022). "The function study showed that GPM6A downregulation enhanced the proliferation, migration, and EMT of lung adenocarcinoma cells, while GPM6A upregulation inhibited their development." (PMID 36405247, 2022). "This study aimed to investigate the role of GPM6A in lung adenocarcinoma and its potential mechanism." (PMID 36405247, 2022). "Then, we explored the function of GPM6A in the development of lung adenocarcinoma in vitro and in vivo and the potential mechanism of GPM6A in lung adenocarcinoma cells." (PMID 36405247, 2022). "However, GPM6A inhibits lung adenocarcinoma progression via inhibiting phosphoinositide 3‐kinase (PI3K)/AKT serine (AKT) pathways." (PMID 39957375, 2025).
lung adenocarcinoma (continued). "When analyzing the expression of GPM6A mRNA in cancer using The Cancer Genome Atlas (TCGA) dataset, it was found that downregulation of GPM6A enhanced the migration, proliferation, and EMT of lung adenocarcinoma cells, whereas upregulation of GPM6A inhibited their development." (PMID 39957375, 2025). "Downregulation of GPM6A enhanced EMT of lung adenocarcinoma cells and vice versa." (PMID 39957375, 2025). "In summary, GPM6A inhibits the progression of lung adenocarcinoma via inhibiting PI3K/AKT pathway." (PMID 39957375, 2025). "Given that GPM6A is associated with stress, we detected PI3K, p-PI3K, AKT, and p-AKT expression at the protein level and found that GPM6A downregulation promoted the progression of lung adenocarcinoma cells." (PMID 36405247, 2022). "Furthermore, the Kaplan–Meier plot revealed that lung adenocarcinoma patients with lower GPM6A expression had worse prognosis." (PMID 36405247, 2022). "We further investigated the possible mechanism of GPM6A in lung adenocarcinoma cells." (PMID 36405247, 2022). "Importantly, we demonstrated that GPM6A suppressed lung adenocarcinoma progression via inhibition of the PI3K/AKT pathway." (PMID 36405247, 2022). "However, the expression of GPM6A decreases in lung adenocarcinoma, liver cancer, thyroid cancer, and so forth as the tumor progresses, indicating that it may be a tumor suppressor gene." (PMID 39957375, 2025). "On the other hand, the expression of GPM6A decreases in lung adenocarcinoma, liver cancer, thyroid cancer, and so forth as the tumor progresses, and it can inhibit the progression of malignant tumors by inhibiting some signaling pathways, suggesting that it may be a tumor suppressor gene." (PMID 39957375, 2025). "However, evidence on the role of GPM6A in lung adenocarcinoma is limited." (PMID 36405247, 2022). "Therefore, GPM6A might suppress lung adenocarcinoma progression via inhibition of the PI3K/AKT pathway." (PMID 36405247, 2022). "In GB, GPM6A is positively correlated with ZEB1, which promotes EMT, while in lung adenocarcinoma, downregulation of GPM6A can enhance EMT." (PMID 39957375, 2025).
rectal cancer (3 papers, 2021 to 2025). A primary or metastatic malignant neoplasm that affects the rectum. "GPM6A is closely related to the survival time of patients with rectal cancer and is a marker of poor prognosis of rectal cancer." (PMID 39957375, 2025). "GPM6A is related to poor prognosis in patients with rectal cancer or CRC." (PMID 39957375, 2025).
acute myocardial infarction (2 papers, 2022 to 2023). Necrosis of the myocardium, as a result of interruption of the blood supply to the area. "However, there is evidence GPM6A and CHRNA9 may be involved in myocardial development and repair and GPM6A is differentially expressed with respect to acute myocardial infarction." (PMID 37533055, 2023). "There may be hsa_circ_0001147/hsa-miR-204-5p/GPM6A axis, hsa_circ_0004771/hsa-miR-629-3p/SRSF1 axis, hsa_circ_0061276/hsa-miR-629-3p/SRSF1 axis, hsa_circ_ 0045519/hsa-miR-298/ANK2 axis and hsa_circ_0004561 hsa-miR-298/ANK2 axis regulatory relationship involved in myocardial infarction." (PMID 35872921, 2022). "Therefore, there may be hsa_circ_0001147/hsa-miR-204-5p/GPM6A axis, hsa_circ_0004771/hsa-miR-629-3p/SRSF1 axis, hsa_circ_0061276/hsa-miR-629-3p/SRSF1 axis, hsa_circ_0045519/hsa-miR-298/ANK2 axis, and hsa_circ_0004561 hsa-miR-298/ANK2 axis regulatory relationship involved in myocardial infarction." (PMID 35872921, 2022).
breast carcinoma (2 papers, 2010 to 2025). "Luminal cells subset 2 consisted of cells expressing genes ENTPD3, SRRM3, and GPM6A (corresponding to breast cancer-related genes)." (PMID 40573402, 2025). "It is interesting to note that of the nine 1.2 μM MMC(T60)-responsive genes, GPM6A and CDCP1 are tagged with single nucleotide polymorphisms that are shown by CGEMS to be associated with breast cancer risk (P<0.05) (data not shown)." (PMID 20174566, 2010).